SIRT1 (sirtuin 1)
Diseases named in the same sentence as SIRT1 in open-access papers (continued):
Sharing a sentence is not in itself a finding about the gene and the disease.
cancer (continued). "Our findings suggest a crucial function of SIRT1 in inhibiting CHK2 as a potential therapeutic target for cancer treatment." (PMID 30902968, 2019). "On the other hand, SIRT1 promotes cell growth and proliferation in most cancers, such as leukemia and thyroid and colorectal cancers." (PMID 31817470, 2019). "RSV is a natural polyphenol compound that is well-known as a potent SIRT1 activator and has been reported to have beneficial effects against aging and various human diseases including cancer." (PMID 31440387, 2019). "As a result, SIRT1 is also upregulated in various cancers, including melanoma, colon, prostrate, breast, liver, lymphoma, leukemia and sarcomas." (PMID 31043584, 2019). "SIRT1 regulates cancer cell growth and has been identified as a tumor suppressor in retinoblastoma and can be modulated in cancer by deacetylate histones." (PMID 31683808, 2019). "SIRT1 is the most studied of these seven SIRT members in human cancer and plays dual roles in numerous malignancies including OC." (PMID 31572453, 2019). "Recently, studies also demonstrate that SIRT1 overexpression is responsible for chemoresistance in cancers." (PMID 31056532, 2019). "By deacetylating Smad4 and lessening the impact of TGF-β signaling on MMP7, SIRT1 decreases epithelial to mesenchymal transition (EMT) in cancer and fibrosis." (PMID 31817470, 2019). "In line with our data, a predominant cytoplasmic localization of SIRT1 has been reported in a group of cancer cells, owing to aberrant PI3K/IGF-1R signaling." (PMID 30038266, 2018). "SIRT1 is well known to involve extensively in many physiological as well as pathological conditions such as aging, cancer, neurodegenerative diseases and metabolic processes." (PMID 30619275, 2018). "Accumulating evidence indicates that SIRT1 is a key regulator of diverse life events, including life span extension, inflammation, and cancer." (PMID 30377410, 2018). "Overall, our findings suggest that the negative regulation between CPEB1 and SIRT1 contributes to the suppression of cancer stemness in HCC." (PMID 30237545, 2018). "Fourth, in cancer cells, SIRT1 overexpression induced a G1-phase cell cycle arrest via cyclin D1 signaling, an effect that is in line with our finding on RA-FLS cell cycle arrest." (PMID 29784872, 2018). "Several studies have identified that ectopic expression of miR-34a is related to cell cycle, proliferation, migration, invasion,apoptosis and prognosis of cancers by targeting AXL/ SIRT1/Yin Yang-1." (PMID 29298665, 2018). "In this study, we have demonstrated that CPEB1 directly regulates sirtuin 1 (SIRT1) mRNA to mediate cancer stemness in HCC." (PMID 30237545, 2018). "A thorough understanding of the impact of miR-34a on HTLV-1-infected T-cells is worthy of further study, given the current interest in the use of miR-34a mimics, nutlin-3a analogs, and SIRT1 inhibitors to treat various cancers." (PMID 29780367, 2018). "The authors showed that SIRT1 represses basal and inducible expression of estrogen-responsive genes, while inhibition of SIRT1 activity results in transcriptional activation of estrogen-responsive genes and consequently, cancer cell proliferation." (PMID 30380732, 2018).
cancer (continued). "Of note, some achievements have been made in cancer therapies targeting SIRT1 with autophagy mechanisms." (PMID 29991742, 2018). "SIRT1 widespread regulation of multiple cancer-related enzymes often leads to its multifaceted functions in various cancers." (PMID 30093977, 2018). "For example, SIRT1 increased skeletal muscle proliferation, but inhibited proliferation of endothelial cells and certain cancer cell types." (PMID 29784872, 2018). "Nevertheless, several reports have demonstrated that the knockdown of SIRT1, SIRT2, or SIRT1/2 genes affected less cancer cell viability but essentially proliferation and/or invasion." (PMID 29401749, 2018). "The interplay between c-MYC and SIRT1, therefore, plays a relevant role during PC tumorigenesis and should be taken into account when designing strategies aimed at combating this cancer." (PMID 30319549, 2018). "Some research has found that SIRT1 can inhibit NF-κB activation and facilitate cancer cell apoptosis, but other studies reported that SIRT1 contributes to cell autophagy and then promotes cell survival." (PMID 29416748, 2018). "HDAC SIRT1 embodies these properties, and orchestrates the regulation of multiple cancer-related genes through histone deacetylation." (PMID 30380732, 2018). "Knockdown of SIRT-1 was found to be able to increase the sensitivity of cancer cells to chemotherapy." (PMID 29552311, 2018). "Yet researchers have long been baffled by SIRT1 contradictory actions in the carcinogenesis process, and its involvement in cancer biology remains an open question." (PMID 30380732, 2018). "SIRT1 inhibitors have been effective in sensitizing a variety of cancer cell lines to DNA-damaging agents, including radiation." (PMID 29717261, 2018). "We found in RA-FLS, SIRT1 overexpression significantly inhibited cell proliferation and arrested cell cycle, consistent with previous reports showing SIRT1 as an inhibitor against cell proliferation in certain proliferative diseases such as cancer." (PMID 29784872, 2018). "SIRT1 is also a target for several miRNAs, small non-coding RNA molecules known to be deregulated in various cancers, whose expression is involved in tumorigenesis." (PMID 30319549, 2018). "SIRT1 can deacetylate histone H4 lysine 16 (H4K16), whose hypoacetylation is a hallmark of human cancer." (PMID 30377410, 2018). "Of particular interest to CRC and cancer in general is also SIRT1’s influence on glucose and lipid metabolism, considering that altered cell metabolism is one of the a hallmarks of cancer." (PMID 30410074, 2018). "SIRT1 is a histone deacetylase that links the metabolic status of the cell to regulation of gene expression and numerous other processes with relevance to cancer, such as apoptosis, genetic stability, inflammation, immune response, and autophagy." (PMID 30410074, 2018). "Alterations of the level of SIRT1 expression were determined in several diseases including metabolic diseases, neurodegenerative diseases, cancer and aging." (PMID 30374331, 2018). "NAD+-dependent deacetylase SIRT1 belongs to the most conserved longevity genes that link metabolism to stress response, endocrine mechanism, aging, and cancer." (PMID 30038266, 2018). "In cancer, the role of SIRT1 is controversial since it can function as both a tumor promoter and tumor suppressor." (PMID 30377410, 2018). "The role of SIRT1 in promoting tumor metastasis provides a rational explanation for the poor prognosis of cancer patients with high SIRT1 expression." (PMID 29374154, 2018). "It has been shown that activation of SIRT1 by resveratrol, a known activator of SIRT1, leads to decreased expression of various cyclins in several cancer cell lines." (PMID 29487709, 2018).
cancer (continued). "SIRT1 modulators have been discovered or designed, and clinical studies investigating the therapeutic potential of SIRT1 in cancer treatment hold promising results." (PMID 30380732, 2018). "Salermide mediates apoptotic cell death; this is dependent on the activation of proapoptotic genes that are directly or indirectly suppressed by SIRT1 in cancer cells." (PMID 30217020, 2018). "We also assessed the possibility that CPEB1 directly regulates sirtuin 1 (SIRT1) to mediate cancer stemness in HCC through an interaction with a CPE site." (PMID 30237545, 2018). "Here, we identified that the sequiterpene alkaloid eurochevalierine displays a selective sirtuin 1/2 inhibitory profile, which provide a novel chemical scaffold for the lead compound development of SIRT1- and 2-based cancer therapy." (PMID 29401749, 2018). "The sirtuin family was identified as a major target of NAD+, and among its members, SIRT1 is widely studied in cancer development." (PMID 30513573, 2018). "In fact, our investigations indicate anti-proliferative effects of 1,25(OH)2D3 to depend on SIRT1 activity in Thc and cancer cells." (PMID 30271381, 2018). "Previously, we reported that amurensin G, a natural SIRT1 inhibitor, enhanced susceptibility of MDR cancer cells to Hsp90 inhibitors, but clinical trial of amurensin G have not been performed yet." (PMID 29541415, 2018). "Sirtuins, whose family consists of seven members (SIRT1-7), are important targets for cancer therapy, being up-regulated in several types of cancer." (PMID 35542353, 2018). "Other studies have shown the role of SIRT1 in the biology of liver tumors containing cancer stem cells." (PMID 29584707, 2018). "In our study, we paid close attention to the potential target for cancer therapies, SIRT1, and focused on searching for a proper compound as a SIRT1-targered activator." (PMID 29991742, 2018). "MiR-34a exerts its regulative role for cell cycle, differentiation, apoptosis, cancer cell progression and metastasis by targeting genes such as SIRT1, Bcl-2 and HMGI-C." (PMID 29854296, 2018). "An increasing number of studies have shown that SIRT1 plays a crucial role in tumor metastasis and invasiveness in various cancers." (PMID 29374154, 2018). "For example, SIRT1-dependent deacetylation of prototypic Myc oncogenes, c-Myc and N-Myc, enhances their stability and transcriptional activity, resulting in cancer cell survival and proliferation, respectively." (PMID 30380732, 2018). "Sirt1 is known to be involved in a number of physiological processes, including apoptosis, cell differentiation, development, autophagy, and cancer metabolism, as well as circadian rhythms." (PMID 29643977, 2018). "The focus of this review is the role and involvement of SIRT1 in secretory organ cancers since the information recently gathered on this topic should bear new translational benefits." (PMID 30319549, 2018). "In these studies, AMPK and OGT seem to have opposite effects on various proteins involved in cancer metabolism, such as the transcriptional regulator hypoxia-inducible factor-1α and the deacetylase sirtuin 1 (SIRT1)." (PMID 30271380, 2018). "In particular, it has been shown that inhibition of sirtuin 1 and 2 activities is beneficial for cancer treatment." (PMID 29401749, 2018).
cancer (continued). "Studies have demonstrated that SIRT-1 participated in the oncogenic signaling pathway of several cancers." (PMID 29552311, 2018). "SIRT1 plays a dual role either in cancer promotion or suppression, depending on different cellular contexts or its targets in specific signaling pathways or specific cancers." (PMID 28600541, 2017). "Recent studies have demonstrated that SIRT1 protects cancer cells from apoptotic signaling when they are treated with DNA-damaging agents." (PMID 29228612, 2017). "All these studies suggested that cytoplasmic expression of Sirt1 is a worse indicator of poor prognosis in cancer patients than the nuclear expression of Sirt1." (PMID 29029516, 2017). "The role of the deacetylase SIRT1 in cancer is not clearly understood and seems to be dependent on cell type and stimulus." (PMID 29383100, 2017). "Among the sirtuins family, the involvement of SIRT1 in cancer has been most extensively studied, which results are decisively controversial and contradictory." (PMID 28600541, 2017). "SIRT1 is known to regulate pro-survival events and play roles in lifespan extension, apoptosis, age-related disorders, inflammation, and cancers." (PMID 29225581, 2017). "Resveratrol, SIRT1 activator, has multiple biological effects, such as antioxidant activity, anti-inflammatory and anti-cancer." (PMID 28903430, 2017). "SIRT1 is highly expressed in various types of cancer, including breast, colon, and non-small cell lung cancer." (PMID 29312612, 2017). "As cellular SIRT1 was reported to protect cancer cells from the DNA-damaging agents, we detected the expression of SIRT1 in PrEC cells and PCa cell lines C4-2 and LNCaP." (PMID 29228612, 2017). "Increasing evidence suggests that SIRT1 promotes Wnt/β‐catenin signaling in both normal progenitor and cancer cells by a variety of mechanisms." (PMID 28994177, 2017). "In coherence with their strategic role in cellular protection, both SIRT1 and 3 are frequently over-expressed in several type of cancers, and contribute to chemo- and radio-resistance." (PMID 28904402, 2017). "Thus, SIRT1 relocation in response to oxidative stress might have a crucial role in the establishment of aberrant epigenetic patterns associated with the development of pathologies, including cancer." (PMID 29383100, 2017). "The SIRT1 protein deacetylase is reported to have a remarkably wide spectrum of biological functions affecting such varied processes as aging, cancer, metabolism, neurodegeneration and immunity." (PMID 28273169, 2017). "The heterogeneity observed in our combined analysis of colorectal studies was also possibly due to the complex role of SIRT1 in this particular cancer." (PMID 28977971, 2017). "Many studies have shown contradictory roles for SIRT1 either promoting cancer cell survival or accelerating cell death in a variety of cancer types." (PMID 28061480, 2017). "Sirtuin-1 (SIRT1), which is a member of sirtuin family, plays a dual role either in cancer promotion or suppression." (PMID 28600541, 2017). "The aim of the current study was to estimate the role of SIRT1 in relation to OS in cancers of the digestive system." (PMID 28977971, 2017). "Histological studies have revealed increased and decreased expression patterns for Sirt1, depending on cancer type and/or stage." (PMID 29187201, 2017). "Although the role of SIRT1 in cancers is still controversial, SIRT1 has been indicated to be a key target for resveratrol in several human tumor models." (PMID 28600541, 2017). "Early studies identifies that resveratrol activates SIRT1 and inhibits tumor development in SIRT1-dependent manner in cancer cells, nude mice or transgenic mice." (PMID 28903430, 2017).
cancer (continued). "Inhibition of SIRT1 has been shown either to inhibit the growth of cancer cells or to reduce the tumor burden in animal models." (PMID 28977971, 2017). "Several studies have defined the targets of miR-138 such as VIM, RhoC, Hif-1α, CCND1 and Sirt1 in cancer types other than RCC, which are often involved in cell migration, EMT, DNA damage repair, senescence." (PMID 28978010, 2017). "Previous studies have also demonstrated that SIRT1 is overexpressed in some cancers and correlates with poor prognosis due to its promotion of tumor metastasis." (PMID 28052003, 2017). "Sirtuin1 (SIRT1), a histone deacetylase has been reported to positively regulate autophagy and thus has a multi-functional role in inflammatory diseases and cancer." (PMID 28678839, 2017). "Additional and more in-depth clinical studies are needed because current studies indicate that Sirt1 can serve as a more accurate prognostic predictor in carcinomas." (PMID 29029516, 2017). "Altogether, the results of our analyses strongly support the current mainstream point that Sirt1 redundancy was significantly correlated with patient overall survival in carcinomas." (PMID 29029516, 2017). "Our study provides a better understanding of the controversial roles of SIRT1 in cancer promotion and also an important consideration in developing SIRT1-targeting anticancer agents." (PMID 26992208, 2016). "Among other Nε-thioacetylated pseudopeptide inhibitors developed to improve potency, selectivity, and cell permeability, compounds 29 and 30 were found to be micromolar inhibitors of SIRT1-3 and showed antiproliferative effects on cancer cells." (PMID 27226812, 2016). "Although this is an opposite impact to that observed in LoVo cells, it is logical and in agreement with the proposal that metformin induced apoptosis in cancer cell lines, whilst in healthy tissues, promotes cell survival, likely via SIRT1/FOXO axis." (PMID 27588026, 2016). "Together, these data suggest that LSD1 and SIRT1 oppositely regulate cellular NHEJ repair and acquisition of genetic mutations in cancer cells in response to DNA damage or therapeutic stress, a phenotype consistent with their opposing interaction with KU70." (PMID 27384990, 2016). "Increasing evidence shows that human Sirt1 is highly expressed in cancer cell lines and that a strong cytosolic component exists in the Sirt1 expression pattern." (PMID 27171144, 2016). "Repression of EMT in cancer and fibrosis was regarded as the result of SIRT1-mediated inhibition of the TGF-β signaling pathway via Smad4 deacetylation, with consequent decreased MMP7 expression, E-cadherin degradation, and β-catenin nuclear translocation." (PMID 27379175, 2016). "Migration and invasion are key processes that facilitate cancer progression and SIRT1 is known to increase these processes." (PMID 26988912, 2016). "Currently, the role of SIRT1 in cancer is controversial, due to the Janus-faced activity of SIRT1 in tumorigenesis." (PMID 27081083, 2016). "We further confirm that, for the first time, the downregulation of tNOX concurrently with decreased SIRT1 contribute to the reduced cancer phenotypes, including enhanced apoptosis, increased cell doubling time, and decreased cell migration." (PMID 27367652, 2016). "Our transfection experiments showed that mol-miR168a identified by MirCompare-COMIR software inhibited translation of SIRT1 mRNA in cancer cells." (PMID 26930203, 2016). "SIRT1 is a multifaceted NAD+-dependent protein deacetylase known to act as a tumor promoter or suppressor in different cancers." (PMID 27081083, 2016). "In a colony-forming assay reflecting anchorage-independent cancer growth, cell colonization within agar matrix was inhibited in cancer cells overexpressing SIRT1." (PMID 26992208, 2016).